CHKB-DT (CHKB divergent transcript)
Synonyms: TCONS_00029632; HRAT; CHKB-AS1
Gene: Long non-coding RNA gene on chromosome 22 (50,583,026 to 50,597,599, forward strand). Ensembl gene ENSG00000205559.
Diseases named in the same sentence as CHKB-DT in open-access papers:
CHKB-DT is named in the same sentence as 2 diseases in open-access papers, as found by Europe PMC text mining. Sharing a sentence is not in itself a finding about the gene and the disease.
CHKB-DT shares sentences with these, for which no sentence is quoted: tumor (3 papers); myocardial infarct (1).